LY6K (lymphocyte antigen 6 family member K)
Diseases named in the same sentence as LY6K in open-access papers (continued):
Sharing a sentence is not in itself a finding about the gene and the disease.
gastric cancer (8 papers, 2014 to 2022). A primary or metastatic malignant neoplasm involving the stomach. "Overexpressed in several malignant tumours (including gastric cancer), LY6K derives peptide LY6K‐177 (RYCNLEGPPI) designed for this target, and the latter can be seen as a promising CPP in immunotherapy." (PMID 35593206, 2022). "The survival data for colorectal, ovarian and gastric cancer showed that all four studied genes Ly6D, Ly6E, Ly6H, Ly6K are poor prognosis markers for multiple cancer types." (PMID 26862846, 2016). "Ly6K mRNA expression was significantly higher in gastric cancer grade 3 (n=18) than grade 2 (n=6) in Forster study." (PMID 26862846, 2016). "LY6K peptide vaccine was studied in a fixed dose in six patients with advanced gastric cancer." (PMID 29587677, 2018). "Recently, clinical trials in patients with gastric cancer (GC) have been conducted using peptide-based vaccines, including vascular endothelial growth factor receptor 2- (VEGFR2-) 169, VEGFR1-1084, and lymphocyte antigen 6 complex locus K (LY6K-177) epitope peptides." (PMID 26568964, 2015).
lung carcinoma (8 papers, 2013 to 2024). "The LY6 family, consisting of Ly6D, Ly6E, Ly6K and Ly6H, is also associated with poor survival in several cancer types, including lung cancer." (PMID 35574342, 2022). "LY6K has been shown to stimulate cytotoxic T lymphocytes that recognized and killed esophageal and lung cancer cells that express these proteins." (PMID 39727968, 2024). "Vaccination with two epitope peptides derived from LY6K (also named URLC10) and cell division associated 1 (CDCA1) induced specific CTLs (Cytotoxic T lymphocytes) expressing various TCRs in vaccinated lung cancer patients." (PMID 35574342, 2022). "The increased expression of LY6D, LY6E, LY6K, and LY6H was associated with poor survival in ovarian, colorectal, gastric, breast, and lung cancer." (PMID 31068932, 2019). "Ly6K mRNA expression was significantly increased in 375 samples of lung cancer than 143 samples of normal tissue in Hou, Selamat, Okayama studies." (PMID 26862846, 2016). "Survival data for breast and lung cancer show that Ly6D, Ly6E and Ly6K were poor prognosis marker for these cancers." (PMID 26862846, 2016). "Upregulated in lung cancer 10 (URLC10), also known as lymphocyte antigen 6 complex locus K (LY6K), were shown to be over-expressed in several cancers." (PMID 29587677, 2018).
non-small cell lung carcinoma (7 papers, 2011 to 2024). A group of at least three distinct histological types of lung cancer, including non-small cell squamous cell carcinoma, adenocarcinoma, and large cell carcinoma. "LY6K overexpression is associated with poorer prognosis for patients with non-small cell lung carcinomas as well as oesophageal squamous cell carcinomas." (PMID 21063397, 2011). "While in non-small cell lung cancer, miR-500a-3p acts as a tumor suppressor via downregulating LY6K expression." (PMID 35241106, 2022). "Ly6K mRNA expression was significantly higher in cohort of squamous lung carcinoma (n=309) than cohorts of non small cell lung carcinoma (n=218) in TCGA, Bild, Lee, and Hou studies." (PMID 26862846, 2016). "Silencing of LY6K reduced the proliferation of CCSCs, which is consistent with previous studies, demonstrating that LY6K downregulation inhibits proliferation through the miR-500a-3p signaling axis in non-small cell lung cancer." (PMID 39727968, 2024).
cervical cancer (6 papers, 2014 to 2023). A primary or metastatic malignant neoplasm involving the cervix. "Furthermore, the Cancer Genome Atlas (TCGA) database and Gene Expression Omnibus (GEO) cohort were used to analyze LY6K mRNA expression in association with the pathological characteristics, where LY6K was upregulated during higher grade in cervical cancer patients." (PMID 37076981, 2023). "In higher‐grade cervical cancer patients, elevated LY6K expression level was observed correlating with poor prognosis." (PMID 37076981, 2023). "Since the proliferation propensity of LY6K‐depleted cervical cancer cells is low, the enhanced EGF signaling pathway was further resolved." (PMID 37076981, 2023). "Our study demonstrates the key role of LY6K in both clathrin‐ and CAV‐1‐mediated endocytic pathways regulated by TGF‐β and EGF, and it suggests a correlation between LY6K overexpression in cervical cancer cells and poor overall survival." (PMID 37076981, 2023). "In conclusion, LY6K contributes to cervical cancer metastasis by regulating TGF‐β and EGF receptors and their signaling pathways." (PMID 37076981, 2023). "Short interfering RNA (siRNA) was used to knockdown the expression of LY6K in human cervical cancer patients." (PMID 37076981, 2023). "Since TGF‐β‐ and EGF‐induced proliferation, migration, and invasiveness are affected in LY6K‐depleted cervical cancer cells, the effect of TGF‐β and EGF on signaling pathways was further studied in such cells." (PMID 37076981, 2023). "Since LY6K depletion affected downstream signals of TGF‐β and EGF, including invasiveness and proliferation of cervical cancer cells, it is possible that LY6K is an important regulator of signal transduction of ligands at the plasma membrane level." (PMID 37076981, 2023). "LY6K showed higher expression in HPV− when compared to HPV+ HNSCC but showed high expression in HPV+ cervical cancer cell lines." (PMID 30655605, 2019). "Ly6K mRNA expression was significantly increased in 40 samples of cervical cancer than 5 samples of normal tissue in Biewenga study." (PMID 26862846, 2016). "Cervical cancer patients with high levels of LY6K expression showed poor OS." (PMID 37076981, 2023). "Among these, LY6K was significantly upregulated in lung and cervical cancer tissues than in others." (PMID 37076981, 2023). "LY6K is known to play a role in several cancers, including HPV-associated cervical cancer." (PMID 30655605, 2019). "We also observed overexpression of LY6K in HPV+ cervical cancer cell lines." (PMID 30655605, 2019). "Indeed, high LY6K expression was observed in human cervical cancer cells viz." (PMID 37076981, 2023). "Additionally, since high plasma membrane‐localized expression level of LY6K is observed in cervical cancer patients, it may be therapeutically targeted by chimeric antigen receptor‐NK and T cells." (PMID 37076981, 2023). "In this study, we explored the effects of LY6K on TGF‐β and EGF signaling pathways in cervical cancer cells." (PMID 37076981, 2023). "Since LY6K is a GPI‐anchored protein and its depletion downregulates the proliferation, migration, and invasion of cervical cancer cells, the signal transduction mechanisms were explored at surface receptor level." (PMID 37076981, 2023). "Therefore, LY6K depletion suppresses the effects of EGF and TGF‐β along with the basal levels of proliferation, migration, and invasiveness in cervical cancer cells." (PMID 37076981, 2023).
esophageal squamous cell carcinoma (6 papers, 2012 to 2024). Esophageal squamous cell carcinoma (ESCC) is a type of esophageal carcinoma (EC) that can affect any part of the esophagus, but is usually located in the upper or middle third. "Additionally, LY6K is a target for cancer vaccine therapies because stimulating cytotoxic T lymphocytes by endogenously expressed LY6K presents a specific cytotoxic activity against lung and esophageal squamous cell carcinoma." (PMID 27494879, 2016). "A phase I trial for advanced esophageal squamous cell carcinoma in patients with HLA-A*2402 demonstrated that a combination of LY6K and TTK with CpG-7909 elicited potent LY6K-specific T cell responses." (PMID 39727968, 2024).
ovarian carcinoma (5 papers, 2016 to 2024). A malignant neoplasm originating from the surface ovarian epithelium. "ZNF252P-AS1, which is involved in our risk model, has been demonstrated to facilitate ovarian cancer progression via miR-324-3p/LY6K signaling." (PMID 36309694, 2022). "Likewise, qRT-PCR results indicated that LY6K is dramatically up-regulated in ovarian cancer cells associated with standard ovarian cells." (PMID 34980214, 2022). "In conclusion, by using a systematic approach of evaluating and prioritizing TAAs, we have identified KIF20a, CT45, and LY6K to be highly suitable targets for targeted T cell therapy in ovarian cancer." (PMID 36768616, 2023). "In this study, LY6K expression was lifted in the tissues of ovarian cancer patients, and higher level of LY6K was found in recurrent cancer patients." (PMID 34980214, 2022). "We validated that in ovarian cancer cells miR-324-3p directly targeted and negatively regulated LY6K." (PMID 34980214, 2022). "Up-regulation of LY6K significantly enhanced ovarian cancer cell proliferation, while up-regulating miR-324-3p and LY6K neutralized this effect." (PMID 34980214, 2022). "In the current work, we found that over-expression of LY6K accelerated ovarian cancer cell growth, invasion, migration, and EMT process, whereas restrained cancer cell apoptosis." (PMID 34980214, 2022). "The Kaplan–Meier postoperative survival curve for ovarian cancer patients and LY6K expression showed that high LY6K levels were related with poor ovarian cancer prognosis." (PMID 34980214, 2022). "Analyzed findings found that LY6K is higher in ovarian cancer tissues relative to normal controls and is more pronounced in recurring ovarian cancer tissues compared to cancer tissues." (PMID 34980214, 2022). "ZNF252P-AS1, miR-324-3p, and lymphocyte antigen 6 family member K (LY6K) expression were analyzed by bioinformatics tools in ovarian cancer tissues and was quantified by qRT-PCR in ovarian cancer cells." (PMID 34980214, 2022). "In this report, we found that ZNF252P-AS1 can competitively bind miR-324-3p to enhance LY6K expression, thereby promoting the proliferation, migration and invasion, and inhibiting the apoptosis of ovarian cancer cells." (PMID 34980214, 2022). "ZNF252P-AS1 and LY6K levels were up-regulated, while miR-324-3p was declined in ovarian cancer tissues and cells." (PMID 34980214, 2022). "Taken together, our results suggested that miR-324-3p targeted and adversely adjusted LY6K in ovarian cancer." (PMID 34980214, 2022). "Collectively, miR-324-3p over-expression promoted apoptosis and inhibited viability, migration, invasion, and EMT of ovarian cancer cells by negatively regulating LY6K." (PMID 34980214, 2022). "Ly6K mRNA expression was significantly higher in cohort of ovarian cancer (n=8) than cohorts of precursors (n=24) in Buchholz study and ovarian cancer (n=361) than borderline tumor (n=57) in Bittner(Unpublished, GSE2109), Anglesio and Tothill studies." (PMID 26862846, 2016). "High Ly6K mRNA expression in ovarian cancer was significantly correlated with poor five-year overall survival (low Ly6K, n=96; high Ly6K, n=97; HR=1.3, p=0.0008) shown by PROGgeneV2." (PMID 26862846, 2016). "However, a study of ZNF252P AS1 in ovarian cancer showed that miR-324-3P overexpression promotes the apoptosis of ovarian cancer cells by negatively regulating LY6K." (PMID 39727968, 2024). "Interestingly, we observed differences between relatively low mRNA expression of LY6K in the ovarian cancer dataset and detectable LY6K in nearly all tumor samples investigated on protein level by IHC." (PMID 36768616, 2023). "Overexpression of LY6K could refrain the apoptosis of ovarian cancer cells, while overexpressing miR-324-3p and LY6K could alleviate this effect." (PMID 34980214, 2022). "Besides, a higher expression of LY6K was closely related to poor prognosis in ovarian cancer patients, which is consistent with previous reports." (PMID 34980214, 2022).
ovarian carcinoma (continued). "Nevertheless, there are few reports to elucidate the effect of LY6K in ovarian cancer." (PMID 34980214, 2022). "Our work revealed that ZNF252P-AS1 could promote the progression of ovarian cancer cells at least in part via sponging miR-324-3p to upregulate LY6K." (PMID 34980214, 2022). "ZNF252P-AS1 mediated miR-324-3p/LY6K signaling to facilitate progression of ovarian cancer." (PMID 34980214, 2022). "Thus, we subsequently studied LY6K expression in ovary cancer tissue in normal tissues, ovary cancer tissues and recurrent ovary cancer tissues with TCGA-OV data." (PMID 34980214, 2022). "Yet, the specific functions of LY6K in ovarian cancer is largely unknown." (PMID 34980214, 2022). "In this work, we for the first time revealed the expression levels and functions of ZNF252P-AS1 in ovarian cancer and unraveled that ZNF252P-AS1/miR-324-3p/LY6K played significant roles in ovarian cancer." (PMID 34980214, 2022).
triple-negative breast carcinoma (5 papers, 2016 to 2023). An invasive breast carcinoma which is negative for expression of estrogen receptor (ER), progesterone receptor (PR), and human epidermal growth factor receptor 2 (HER2). "This approach will be specifically relevant in hard-to-treat cancers where LY6K is highly expressed, such as cervical, pancreatic, ovarian, head and neck, lung, gastric, and triple-negative breast cancers." (PMID 32098321, 2020). "LY6K mRNA expression was higher in triple-negative breast cancer subtype (TNBC) as compared with other subtypes." (PMID 27494879, 2016). "NSC243928 induces cell death in triple-negative breast cancer cells in a LY6K-dependent manner." (PMID 36900259, 2023). "In cancers with high LY6K expression that were difficult to treat, such as cervical, pancreatic, ovarian, head and neck, lung, stomach, and triple-negative breast cancer, inhibition of LY6K expression through small-molecule binding can be used to inhibit the growth of cancer cells." (PMID 34169093, 2021).
glioma (4 papers, 2016 to 2024). A benign or malignant brain and spinal cord tumor that arises from glial cells (astrocytes, oligodendrocytes, ependymal cells). "Survival data for bladder and brain and CNS cancer showed that Ly6E and Ly6K is poor prognosis marker for these cancers." (PMID 26862846, 2016). "High Ly6K mRNA expression in brain and CNS cancer was significantly correlated with decreased three-year overall survival (dead, n=33 vs alive, n=11) in Freije study." (PMID 26862846, 2016). "A trial using a polypeptide vaccine targeting LY6K, DEPDC1, KIF20A, and FOXM1 in patients with high-grade glioma showed that the vaccine was well tolerated, elicited an effective immune response, and prevented disease progression for at least 6 months." (PMID 39727968, 2024). "Ly6K mRNA expression was significantly higher in Myc amplified brain and CNS cancer (n=12) than cancer without Myc amplification (n=5) in Robinson study." (PMID 26862846, 2016).
colorectal cancer (3 papers, 2016 to 2024). A primary or metastatic malignant neoplasm that affects the colon or rectum. "Although the precise mechanisms underlying LY6K’s oncogenic effects in colorectal cancer remain unclear, previous studies suggest that LY6K overexpression may suppress T-cell development, thereby weakening the immune response against tumors." (PMID 39727968, 2024). "Lymphocyte antigen 6 complex, locus K (LY6K) is a putative oncogene in various human cancers, including colorectal cancer, where elevated expression is associated with poor prognosis." (PMID 39727968, 2024). "LY6K silencing significantly reduced tumor growth and improved survival in a colorectal cancer xenograft model." (PMID 39727968, 2024). "In our xenograft mouse model, LY6K silencing suppressed tumor growth and improved mice survival, supporting its therapeutic potential in colorectal cancer." (PMID 39727968, 2024). "In colorectal cancer, analyses using Oncomine and the Georgetown Database of Cancer have revealed elevated LY6K mRNA levels in tumor tissues compared to adjacent normal tissues, correlating with poor prognosis." (PMID 39727968, 2024). "Further studies are needed to investigate the signaling pathways involved in LY6K-mediated oncogenesis to better understand its role and therapeutic potential in colorectal cancer." (PMID 39727968, 2024). "Ly6K mRNA expression was significantly increased in 273 samples of colorectal cancer than 71 samples of normal tissue in Sabates-Bellver, TCGA and Skrzypczak studies." (PMID 26862846, 2016). "However, the functional role of LY6K in colorectal cancer remains largely unexplored." (PMID 39727968, 2024).
glioblastoma (3 papers, 2016 to 2023). The most malignant astrocytic tumor (WHO grade IV). "Hypomethylation of LY6K promoter increased the expression levels of LY6K, and the increased expression level of LY6K results in poor OS in glioblastoma." (PMID 37076981, 2023). "Previous studies also shows that LY6K is a crucial contributor to tumor biology and functions in glioblastoma tumorigenicity, and knockdown of LY6K in cancer cells leads to reduced tumor growth in mouse models." (PMID 34980214, 2022). "LY6K is reported to promote glioblastoma tumorigenicity through CAV-1-mediated ERK1/2 pathway enhancement." (PMID 34980214, 2022). "Ly6K expression was significantly higher in glioblastoma (n=59) than astrocytoma (n=8) in Freije study." (PMID 26862846, 2016).
head and neck cancer (3 papers, 2016 to 2022). A primary or metastatic malignant neoplasm affecting the head and neck. "Elevated gene expression of Lymphocyte antigen 6K (LY6K) in cancer cells is associated with poor survival outcomes in multiple different cancer types including cervical, breast, ovarian, lung, and head and neck cancer." (PMID 32098321, 2020). "Ly6K mRNA expression was significantly increased in 92 samples of head and neck cancer than 43 samples of normal tissue in Peng, He and Ye studies." (PMID 26862846, 2016). "However, OS was significantly longer in patients with advanced head and neck cancer treated with LY6K, CDCA1, and IMP3 peptides who were A24(+) compared with those who were A24(–); median survival time was 4.9 versus 3.5 months; p < 0.05)." (PMID 38993370, 2022).
Infertility (2 papers, 2016 to 2020). "Although both Tex101−/− and Ly6k−/− mice can produce morphologically intact spermatozoa, both knockout mice show an infertile phenotype due to a disorder of spermatozoa to migrate into the oviduct." (PMID 27005865, 2016).
lung adenocarcinoma (2 papers, 2013 to 2023). A carcinoma that arises from the lung and is characterized by the presence of malignant glandular epithelial cells. "In conclusion, we identified GULPsig, consisting of IGF2BP1, IGF2BP3, SMC1B, CLDN6, and LY6K, as a potential prognostic signature for lung adenocarcinoma patients." (PMID 37655157, 2023). "Compared with the stage I and IIIA samples, the stage II lung adenocarcinoma samples were marked by two differentially-expressed genes (GINS2 and LY6K)." (PMID 24137407, 2013).
astrocytoma (1 paper, 2016). "Ly6K mRNA expression was significantly higher in astrocytoma, grade 4 (n=76) than astrocytoma grade 3 (n=24) in Phillips study." (PMID 26862846, 2016).
brain tumors (1 paper, 2016). "Ly6K expression was significantly higher in recurred brain tumors (n=7) than primary brain tumors (n=20) in Liang study." (PMID 26862846, 2016).
Colon Cancer (1 paper, 2024). "This study investigates the expression and function of LY6K in colon cancer stem cells (CCSCs), both in vitro and in vivo." (PMID 39727968, 2024). "This study investigates the antitumor effects of LY6K in colon cancer stem cells (CCSCs) both in vitro and in vivo." (PMID 39727968, 2024).
colorectal adenocarcinoma (1 paper, 2016). The most common type of colorectal carcinoma. "High Ly6K expression was significantly correlated with higher cancer staging in squamous lung cancer stage N1+ (n=12) than stage N0 (n=25) and in colorectal adenocarcinoma (n=15) than N0 stage in Bittner(Unpublished, GSE2109), study." (PMID 26862846, 2016).